SULT1A3 (sulfotransferase family 1A member 3)
Description:
Sulfotransferase that utilizes 3'-phospho-5'-adenylyl sulfate (PAPS) as sulfonate donor to catalyze the sulfate conjugation of phenolic monoamines (neurotransmitters such as dopamine, (R)- adrenaline/epinephrine, (R)-noradrenaline/norepinephrine and serotonin) and phenolic and catechol drugs. Catalyzes the sulfation of T4 (L-thyroxine/3,5,3',5'-tetraiodothyronine), T3 (3,5,3'-triiodothyronine), rT3 (3,3',5'-triiodothyronine) and 3,3'-T2 (3,3'-diiodothyronine), with a substrate preference of 3,3'-T2 > rT3 > T3 > T4.
Synonyms: ST1A3; TL-PST; STM; HAST; HAST3; M-PST; ST1A3/ST1A4; ST1A4; ST1A5
Tractability: Small molecule: a structure with a bound ligand is known. PROTAC: ubiquitination databases record sites on it.
Target class: Enzyme; Transferase
Gene: Protein-coding gene on chromosome 16 (30,198,059 to 30,204,324, forward strand). Ensembl gene ENSG00000261052.
Subcellular location: Cytoplasm
Pathways (Reactome):
Cellular responses to stimuli: XBP1(S) activates chaperone genes
Drug ADME: Paracetamol ADME
Metabolism: Cytosolic sulfonation of small molecules
Gene Ontology:
Molecular function: amine sulfotransferase activity; aryl sulfotransferase activity; protein binding; sulfate binding; sulfotransferase activity
Biological process: 3'-phosphoadenosine 5'-phosphosulfate metabolic process; cellular response to dopamine; dopamine catabolic process; dopamine metabolic process; epinephrine metabolic process; ethanol catabolic process; flavonoid metabolic process; norepinephrine metabolic process; serotonin metabolic process; sulfation; thyroid hormone metabolic process; xenobiotic metabolic process; sulfur compound metabolic process
Cellular component: cytoplasm; cytosol
Homologues: Orthologues: chimpanzee SULT1A3 (98% identical), macaque SULT1A3 (64% identical), tropical clawed frog sult1b1 (50% identical), zebrafish sult1st2 (49% identical), zebrafish sult1st3 (49% identical), zebrafish sult1st7 (49% identical), zebrafish sult1st9 (49% identical), zebrafish sult1st1 (48% identical), zebrafish sult1st4 (47% identical), tropical clawed frog sult5a1 (40% identical), zebrafish sult5a1 (40% identical), zebrafish sult2st3 (39% identical), and 8 more. Paralogues in human: SULT1A4 (100% identical), SULT1A1 (93% identical), SULT1A2 (90% identical), SULT1C4 (54% identical), SULT1B1 (53% identical), SULT1C2 (51% identical), SULT1C3 (49% identical), SULT1E1 (48% identical), SULT2B1 (37% identical), SULT2A1 (36% identical), SULT4A1 (35% identical), SULT6B1 (31% identical).
Diseases named in the same sentence as SULT1A3 in open-access papers:
SULT1A3 is named in the same sentence as 11 diseases in open-access papers, as found by Europe PMC text mining. Sharing a sentence is not in itself a finding about the gene and the disease. The quoted sentences say what the papers report.
Parkinson's (4 papers, 2022 to 2024). "It is noteworthy that SULT1A4 shares an important paralogous relationship with SULT1A3, and several studies have posited a potential association between the copy number of SULT1A3/4 and neurodegenerative diseases such as Parkinson’s and Alzheimer’s." (PMID 39329723, 2024). "The copy number of SULT1A3/4 is associated with Parkinson's and Alzheimer's disease." (PMID 35530433, 2022).
hepatocellular carcinoma (2 papers, 2022 to 2025). A malignant tumor that arises from hepatocytes. "Lastly, dopamine-mediated upregulation of SULT1A3 markedly enhances the metastatic potential of hepatocellular carcinoma cells." (PMID 40108724, 2025). "It was also shown that SULT1A3 can be induced by glucocorticoid dexamethasone and that this induction depends on the level of the glucocorticoid receptor in the HepG2 hepatocellular carcinoma cell line." (PMID 35892601, 2022). "In hepatocellular carcinoma, SULT1A3/4 promotes epithelial to mesenchymal transition, migration, and invasion after dopamine activation." (PMID 35892601, 2022).
lung carcinoma (1 paper, 2020). "The expression of SULT1A3 should be further explored in KRAS-mutant lung cancer patients." (PMID 33240601, 2020).
neuroblastoma (1 paper, 2022). Neuroblastoma (NB) is the most common solid, extracranial childhood tumor. "In the SK-N-MC neuroblastoma cell line, the activation of extracellular signal-regulated kinase 1/2 and calcineurin, but not cAMP, is required for the induction of SULT1A3/4 by dopamine." (PMID 35892601, 2022).
osteosarcoma (1 paper, 2020). A usually aggressive malignant bone-forming mesenchymal neoplasm, predominantly affecting adolescents and young adults. "Relevant studies have reported that SULT1A3 may be a diagnostic marker for osteosarcoma, and SULT1A3 protein upregulation is closely related to the occurrence and development of cancer." (PMID 33240601, 2020).
tumor (4 papers, 2017 to 2025). "What we did show is that in terms of activity levels, the probe substrate activities of SULT1A3 were significantly higher in most of the tumor samples and in pooled tumor S9 preparation." (PMID 28634336, 2017). "The activities of SULT1A1, SULT1B1, SULT1E1 and SULT2A1 in 9 of 10 samples showed a significant decrease in tumor tissues relative to matched pericarcinomatous tissues, whereas the activities of SULT1A3 in 7 of 10 samples increased." (PMID 28634336, 2017). "It was also shown that SULT1A3/4 are highly expressed in tumor tissue." (PMID 35892601, 2022). "Since the RNAseq analysis after treatment for either 24 or 48 h suggested a potential role of DNA damage response (DDR) in the anti-tumor activity of the regimen combining chidamide and MI-3, qPCR analysis was performed to validate expression of SULT1A3 as representative." (PMID 31590682, 2019). "The mRNA expression levels of SULT1A1, SULT1A3, SULT1E1, and SULT2A1 decreased or drastically decreased in 90% of the tumor samples in comparison with the matched pericarcinomatous samples." (PMID 28634336, 2017). "Thus, using probe substrates, we systematically measured the metabolic functions of SULT1A1, SULT1A3, SULT1B1, SULT1E1, and SULT2A1 in tumor S9 (tHLS9-pooled), pericarcinomatous S9 (nHLS9-pooled), and reference pooled normal human S9 (rHLS9-pooled)." (PMID 28634336, 2017). "Sulfate conjugation by other SULT enzymes (SULT1A3, SULT1E1 and SULT1B1) may result in the activation or inactivation of anti-cancer drugs (e.g., raloxifene, sesamol, fulvestrant, and resveratrol), thereby affecting their anti-tumor effects." (PMID 28634336, 2017).
cancer (2 papers, 2015 to 2020). A tumor composed of atypical neoplastic, often pleomorphic cells that invade other tissues. "Among these, sulfotransferases (SULT1A1, SULT1A2, SULT1A3) and aldo-keto reductases (AKR1C1, AKR1C2, AKR1C3) were shown to contribute to disease progression and/or represent therapeutic targets in hormone-dependent forms of cancer, including EOC." (PMID 26372729, 2015).
SULT1A3 also shares sentences with these, for which no sentence is quoted: Alzheimer disease (1 paper); aneurysm (1); liver cancer (1); neurodegenerative disease (1).